CCL8 (C-C motif chemokine ligand 8)
Diseases named in the same sentence as CCL8 in open-access papers (continued):
Sharing a sentence is not in itself a finding about the gene and the disease.
infection (continued). "Moreover, STAT1-dependent chemokines including CCL5, CCL8, CXCL10, and CXCL11 showed a slight increase during the early stage of infection, the most significant increase occurred after 10 h.p.i, peaking at 24 h.p.i." (PMID 40934228, 2025). "FCPLJ treatment downregulated several inflammatory cytokine genes in the liver, including CCL6/MRP-1, CCL8/MCP-2, CCL12/MCP-5, CCL17/TARC, IL1R1, IL1RN/IL1Ra, NAMPT/PBEF1, and PF4/CXCL4, indicating its potential role in mitigating inflammation during infection." (PMID 40007026, 2025). "A nine-analyte synovial panel consisting of PDGF-B, CXCL5, CXCL11, MCP-2 (CCL8), ANGPT1, TIE2, EGF, NOS3, and Gal-1 distinguished dormant infection from truly aseptic cases with 100% specificity and positive predictive value (sensitivity 22%, negative predictive value 74%)." (PMID 41387890, 2025). "Thus, many immune related proteins are elevated at infection in both cases, such as chemokine ligand 10 (CXCL10), interferon gamma (IFNG), interferon lambda 1 (IFNL1) and chemokine ligand 8 (CCL8)." (PMID 34844191, 2021). "The production of CXCL10 and CCL8 by latently infected monocytes was confirmed by ELISA; the level of both chemokines in the latently infected CD14+ monocytes were significantly increased over mock and UV inactivated infection controls." (PMID 33912186, 2021). "Some of the genes that were similarly modulated by MR766 and Rio-U1 related to cytokine signaling (CXCL10/11, CCL8) and the IFN response (IFIT2, ISG15, OAS2, DDX58, among others), suggesting some degree of similarity in signaling patterns following infection with either virus." (PMID 33405202, 2021). "Our analysis indicates that Cxcl13 but not Ccl8 expression is induced beginning 10 days p.i. until day 30 p.i., a period during infection that closely mirrors when the number of ChAT+ T-cells increased in the colon." (PMID 30973939, 2019). "In our analysis, we observe that a subset of these cytokines reported to be present in the serum also show transcriptional upregulations in PBMCs by 4 days post-infection (IL6, IL1B, IL1RN, CCL8, CXCL10) and by 7 days post-infection (CCL2, CCL3, CSF1, TNF, CXCL1, FAS and CXCL8)." (PMID 27595844, 2016). "Moreover, CCL8 may have a potential interaction with CXCL10, which has been identified as an important gene of early infection in the influenza A pathway." (PMID 38960408, 2024). "Furthermore, the MCPs including CCL2, CCL7, CCL8, and CCL12, which were evaluated in a few studies, might be useful biomarkers to distinguish the infection stages of this disease." (PMID 28752079, 2017). "When measuring mRNA expression levels from BAL cells, chemokines CCL2, CCL5, CCL8, and CXCL10 and receptors CCR5 and CXCR5 were significantly upregulated only in JBNU-22-N01 infection at 7 dpi compared with the negative control." (PMID 40459260, 2025). "In a longitudinal study on SARS-CoV-2 infection of ferrets, upper respiratory cell populations first upregulated CCL8 and CCL9, and cells from nasal wash had increased expression of CCL2, CCL8, CCL9, and CCR5 but not IL-6 at day 3 post-infection." (PMID 32766256, 2020). "Furthermore, of the cytokines whose secretion was elevated by 1,25D treatment after infection (CCL3, CCL4, CCL8, IL-8, and TNF-α), treatment did not induce their secretion from uninfected cells." (PMID 23762029, 2013).
inflammation (6 papers, 2012 to 2024). Aberrant reaction of the microcirculation characterized by movement of fluid and leukocytes from the blood into extravascular tissues. "CCL8 expressed and upregulated in spinal neurons after colonic inflammation, are involved in the maintenance of visceral hyperalgesia via the activation of spinal ERK62." (PMID 36973348, 2023). "Mouse CCL8 is constitutively expressed in the skin and may contribute to chronic eosinophilic inflammation by inducing the accumulation of CD4+ Th2 cells in a mouse model of chronic AD." (PMID 38840912, 2024). "A decrease in MCP2/CCL8 levels may affect the development and progression of local intestinal inflammation and tissue destruction in patients with CD through cellular and molecular interactions between epithelial, immune, and inflammatory cells." (PMID 34788319, 2021). "Bindarit is an anti-inflammatory agent that inhibits MCP-1/CCL2, MCP-3/CCL7 and MCP-2/CCL8 synthesis, acting through the down-regulation of NF-kB pathway, that shows potent anti-inflammatory activity in animal models of both acute and chronic inflammation." (PMID 23077623, 2012).
Bacterial Infections (3 papers, 2017 to 2021). "This protein downregulates the CCL8 which makes the host susceptible to bacterial infections compared to individuals having normal levels of CCL8." (PMID 28235076, 2017). "Moreover, reduced lipopolysaccharide-induced CCL8 production upon LPA3 knockdown in THP-1 cells suggested that increased LPA3, along with autotaxin, contributes to inflammation following bacterial infection." (PMID 29236751, 2017).
cardiac disease (1 paper, 2017). "In our results, the expression of complement component C4a, C4b and inflammation genes Ccl11, Ccl8 were up expressed in older CSCs, indicated that targeting the complement system for the management of cardiac disease maybe a new therapy tool." (PMID 27980224, 2017).
hematological malignancies (1 paper, 2022). "CCL8 has been implicated in macrophage recruitment in several solid tumors, and only a few reports have been published on the role of CCL8 in the pathogenesis of hematological malignancies." (PMID 36072582, 2022).
infectious disease (1 paper, 2012). A disorder directly resulting from the presence and activity of a microbial, viral, or parasitic agent in humans. "Notably, the induction of the cognate chemokine ligands such as CCL2, CCL7, and CCL8 are regulated by IFNs-I in certain infectious diseases." (PMID 22911155, 2012).
psychiatric disorder (1 paper, 2024). A disorder characterized by behavioral and/or psychological abnormalities, often accompanied by physical symptoms. "CCL8 promotes the chemotaxis of pro-inflammatory cells in SCZ, which is closely associated with the pathogenesis of psychiatric disorders." (PMID 38702611, 2024).
CCL8 also shares sentences with these, for which no sentence is quoted: aneurysm (2 papers); coronary artery disease (2); cutaneous melanoma (2); fibrosis (2); leukemia (2); malaria (2); neuropathic pain (2); thyroid cancer (2); uveal melanoma (2); acute disseminated encephalomyelitis (1); acute GVHD (1); acute monocytic leukemia (1); adenocarcinoma (1); aortic valve disease (1); atherosclerotic heart disease (1); autoimmune PAP (1); Autoimmunity (1); breast (1); breast invasive lobular carcinoma (1); Cachexia (1); carcinoma in situ (1); chronic kidney disease (1); Cognitive impairment (1); coinfection (1); colonic polyps (1); colorectal adenocarcinoma (1); contact allergic dermatitis (1); cryptorchidism (1); degenerative disc disease (1); dementia (1).
A further 63 diseases each share a sentence with CCL8 in 1 paper.